ARL3 (ARF like GTPase 3)
Description:
Small GTP-binding protein which cycles between an inactive GDP-bound and an active GTP-bound form, and the rate of cycling is regulated by guanine nucleotide exchange factors (GEF) and GTPase-activating proteins (GAP). Required for normal cytokinesis and cilia signaling. Requires assistance from GTPase-activating proteins (GAPs) like RP2 and PDE6D, in order to cycle between inactive GDP-bound and active GTP-bound forms. Required for targeting proteins to the cilium, including myristoylated NPHP3 and prenylated INPP5E. Targets NPHP3 to the ciliary membrane by releasing myristoylated NPHP3 from UNC119B cargo adapter into the cilium. Required for PKD1:PKD2 complex targeting from the trans-Golgi network to the cilium (By similarity).
Synonyms: ARFL3; JBTS35; RP83
Tractability: Antibody: UniProt places it where antibodies can reach, with medium confidence. PROTAC: ubiquitination databases record sites on it; its protein half-life has been measured.
Gene: Protein-coding gene on chromosome 10 (102,673,731 to 102,714,437, reverse strand). Ensembl gene ENSG00000138175.
Subcellular location: Golgi apparatus membrane; Cytoplasm, cytoskeleton, spindle; Nucleus; Cytoplasm, cytoskeleton, microtubule organizing center, centrosome; Cytoplasm; Cell projection, cilium
Subcellular location (Human Protein Atlas): Basal body; Centrosome; Nucleoplasm; Primary cilium
Pathways (Reactome):
Organelle biogenesis and maintenance: Trafficking of myristoylated proteins to the cilium
Gene Ontology:
Molecular function: GDP binding; GTP binding; microtubule binding; protein binding; GTPase activity; magnesium ion binding
Biological process: cilium assembly; mitotic cytokinesis; post-Golgi vesicle-mediated transport; protein localization to cilium; small GTPase-mediated signal transduction; Golgi to plasma membrane transport; kidney development; photoreceptor cell development; protein localization to ciliary membrane
Cellular component: centrosome; cilium; cytoplasmic microtubule; extracellular exosome; Golgi apparatus; midbody; nucleoplasm; nucleus; photoreceptor connecting cilium; spindle microtubule; cytoplasm; microtubule cytoskeleton; Golgi membrane; spindle
Genetic constraint (gnomAD): Loss-of-function variants: 5 observed, 18.87 expected, observed/expected ratio (o/e) 0.26, 90% interval 0.14 to 0.56. The upper end of that interval is the gene's LOEUF score, 0.56, which puts it in group 2 of 6, group 1 being the genes least tolerant of losing a copy. Missense variants: 126 observed, 177.47 expected, observed/expected ratio (o/e) 0.71, 90% interval 0.61 to 0.82. Synonymous variants: 59 observed, 67.97 expected, observed/expected ratio (o/e) 0.87, 90% interval 0.7 to 1.08.
Homologues: Orthologues: macaque ARL3 (99% identical), rabbit ARL3 (99% identical), mouse Arl3 (98% identical), dog ARL3 (98% identical), guinea pig ARL3 (97% identical), tropical clawed frog arl3 (97% identical), rat Arl3 (97% identical), zebrafish arl3a (95% identical), zebrafish arl3b (95% identical), pig ARL3 (93% identical), chimpanzee ARL3 (76% identical). Paralogues in human: ARL2 (53% identical), ARF3 (47% identical), ARF1 (46% identical), ARF6 (45% identical), ARF5 (44% identical), ARL1 (44% identical), ARF4 (43% identical), TRIM23 (43% identical), ARL5B (41% identical), ARL5A (41% identical), ARL14 (40% identical), ARL4C (40% identical), and 18 more.
Diseases named in the same sentence as ARL3 in open-access papers:
ARL3 is named in the same sentence as 41 diseases in open-access papers, as found by Europe PMC text mining. Sharing a sentence is not in itself a finding about the gene and the disease. The quoted sentences say what the papers report.
ciliopathies (18 papers, 2014 to 2025). "Recently, several studies have described variants in ARL3 associated with retinal dystrophy and other ciliopathies." (PMID 40037334, 2025). "Germline Arl3 knockout mice have phenotypes generally associated with human ciliopathies, including polycystic kidneys and photoreceptor degeneration." (PMID 36598133, 2023). "We propose that ARL3 provides a potential hub in the network of proteins implicated in ciliopathies, whereby perturbation of ARL3 leads to the mislocalization of multiple ciliary proteins as a result of abnormal displacement of lipidated protein cargo." (PMID 30269812, 2018). "These Arl3−/− mice, which represent a null allele, developed a severe ciliopathy phenotype with pronounced cystic kidney disease, pancreatic hypoplasia, ductal plate malformation within the liver, and retinal dystrophy with impaired photoreceptor development." (PMID 30269812, 2018). "Dysregulation of ARL3 is implicated in various diseases, including cancer and ciliopathies." (PMID 38972051, 2025). "BART is described as an ARL3 effector which has also been implicated in ciliopathies, although the role of its ARL3 interaction is unknown." (PMID 33438581, 2021). "We speculate that nonsense mutations in ARL3 in humans could cause more pronounced ciliopathy phenotypes, such as the perinatally lethal ciliopathy Meckel syndrome, and could go some way to explaining why such a fundamental gene has previously not been identified in ciliopathy syndromes." (PMID 30269812, 2018). "Arl3 knock-out mice present a severe ciliopathy phenotype with kidney, liver, pancreas, and retinal dysfunction." (PMID 40037334, 2025). "Primarily localized in the nucleus, USP48 plays a crucial regulatory role in inherited retinal dystrophy (IRD) and ciliopathies by removing the ubiquitination of ARL3 and stabilizing UNC119a." (PMID 38245760, 2024). "Mutations in some members of the ARL subfamily (e.g. ARL3, ARL6, ARL13B) are associated with ciliopathy diseases, emphasising that there is still a wealth of clinically relevant cellular mechanisms to undercover in the ARF family." (PMID 37622523, 2023). "In fact, mutations in Arl13B, the Arl3 GEF, cause the syndromic ciliopathy Joubert syndrome and can cause a reduction of Arl3 activation." (PMID 36598133, 2023). "The ADP-ribosylation factor-like 3 (ARL3) is a ciliopathy G-protein which regulates the ciliary trafficking of several lipid-modified proteins." (PMID 33438581, 2021). "Mutations in ARL3 and CEP120 are rare and relatively new causes of JSRD and other related ciliopathies." (PMID 33297941, 2020). "Arl3 knockout studies in mice demonstrate a multi-organ ciliopathy phenotype, including kidney cysts, liver fibrosis and retinal disease with photoreceptor cell degeneration." (PMID 33297941, 2020). "Arl3 appears to be essential for cilia function as deletion leads to widespread ciliopathy and high levels of embryonic lethality." (PMID 28444310, 2017). "In mice, Arl3 inactivation results in various ciliopathy-related phenotypes including cystic kidney disease and retinal degeneration." (PMID 25405894, 2014). "The regulation of ARL3 is critical for ciliary function, as both its reported GEF, ARL13B, and GAP, RP2, have been implicated in ciliopathies." (PMID 33438581, 2021). "Although Arl3 has not been found to be associated with any ciliopathies, classic ciliopathy manifestations have been reported in Arl3 knockout and Arl3 conditional knockout mice." (PMID 30097558, 2018). "Although no mutations in Arl3 have been identified so far in ciliopathies Arl3(-/-) mice exhibit a ciliopathy related phenotype and die by 3 weeks of age." (PMID 26551564, 2015). "Although DNAAF9 variants have not been reported in persons with ciliopathies, its broad expression pattern in humans and interaction with ARL3 across different tissues indicate that it could have critical roles in tissues with both primary and motile cilia." (PMID 41023246, 2025).
ciliopathies (continued). "Besides ARL13B and ARL3 that are involved in human Joubert syndrome, the IFT complex, HYDIN, and the ODA complex are all confirmed human ciliopathy genes." (PMID 39231220, 2024). "The findings reveal a novel mechanism that one ciliopathy GTPase ARL-13, as a GEF, coordinates with UNC-119, which may act as a GTP-binding stabilizing factor, to properly activate another GTPase ARL-3 in cilia, a regulatory process indispensable for ciliogenesis." (PMID 27102355, 2016).
Joubert syndrome (11 papers, 2015 to 2025). Joubert syndrome (JS) is characterized by congenital malformation of the brainstem and agenesis or hypoplasia of the cerebellar vermis leading to an abnormal respiratory pattern, nystagmus, hypotonia, ataxia, and delay in achieving motor milestones. "This loss of the ability to activate ARL3 disrupts ciliary protein composition, and is thought to be the molecular mechanism behind ARL3-related Joubert syndrome." (PMID 40037334, 2025). "Previously, missense variants in ARL3 were reported to cause Joubert syndrome, characterized by hypoplasia of the cerebellar vermis, developmental delay, renal anomalies, and rod-cone dystrophy." (PMID 33805381, 2021). "Failure to activate Arl3 function through loss of the Arl3 GEF Arl13b causes Joubert syndrome, usually with multiple organ involvement." (PMID 28444310, 2017). "Here we show that the ciliary G-protein Arl13B mutated in Joubert syndrome is the GEF for Arl3, and its function is conserved in evolution." (PMID 26551564, 2015). "ARL3 proteins are present in the cilia and mutations lead to Joubert syndrome in humans." (PMID 35325113, 2022). "Overexpression of Arl13B in mammalian cell lines leads to an increased Arl3·GTP level, whereas Arl13B Joubert-Syndrome patient mutations impair GEF activity and thus Arl3 activation." (PMID 26551564, 2015). "Furthermore, two different amino acid substitutions at residue Arg149 of ARL3 were identified in cases of Joubert syndrome (MIM: 618161), highlighting that different ARL3 amino acid changes can manifest with distinct phenotypes and inheritance patterns." (PMID 40037334, 2025).
Retinal dystrophy (9 papers, 2008 to 2025). Retinal dystrophy is an abnormality of the retina associated with a hereditary process. "Human mutations in the small GTPase Arl3 cause both autosomal recessive and dominant inherited retinal dystrophies." (PMID 36598133, 2023). "In conclusion, our results extended both genotype and phenotype of ARL3 associated retinal dystrophy." (PMID 33748123, 2021). "This study expanded both the phenotype and genotype of ARL3 associated retinal dystrophy." (PMID 33748123, 2021). "Homozygous mutation in ARL3 was identified as a cause of autosomal recessive Joubert syndrome, a neurodevelopmental disorder that may include retinal dystrophy, in two unrelated families." (PMID 34485303, 2021). "ARL3 variants have also been reported in association with retinal dystrophy." (PMID 30269812, 2018). "As yet, Arl3 has not been shown to cause retinal dystrophy in humans,but studies in mice deficient in Arl3, revealed that this protein isessential for photoreceptor and kidney development." (PMID 18490186, 2008).
retinal degeneration (8 papers, 2017 to 2025). Degeneration of the retina. "The Arl3 GAP RP2, on the other hand, causes non-syndromic retinal degeneration, providing more evidence that the impact of excess active Arl3 on cells is more detrimental for retinal photoreceptors than other ciliated cells throughout the body." (PMID 36598133, 2023). "Our results, identifying a novel pathogenic variant in ARL3 in a four-generation family with a dominant IRD, augment the evidence that the ARL3 gene is another cause of non-syndromic retinal degeneration." (PMID 34485303, 2021). "ARL3 has also been implicated as an autosomal recessive cause of Joubert syndrome and non-syndromic retinal degeneration." (PMID 34485303, 2021). "Deletion of Arl13b in the mouse retina leads to mislocalization of rTα and rod PDE6 subunits but faster retinal degeneration than Arl3 deficiency does, suggesting additional functions of ARL13B other than a GEF for ARL3 in rod photoreceptor cells." (PMID 33681987, 2021). "Loss of ARL3 function may impair the trafficking of the lipidated outer segment proteins, leading to outer segment shortening and slow retinal degeneration." (PMID 33805381, 2021). "Both a rod-specific Arl3 knockout mouse or a transgenic mouse overexpressing constitutively active Arl3-Q71L in rods show severe retinal degeneration by 2 months and result in measurable effects on lipidated protein delivery to the outer segment." (PMID 36598133, 2023). "Null mice models for arl3 have a defective cilium-dependent signaling influencing different pathways, including Shh and show retinal degeneration." (PMID 34124035, 2021). "Consistently, retinal degeneration was observed in Arl3 KO mice, and mutant arl3 alters ciliogenesis in C. elegans, with an important consequence on cilia signaling." (PMID 34124035, 2021). "Consistent with Unc119 and Pde6d deficiency, Arl3 conditional knockout mice show trafficking defects of lipidated proteins including rTα, rTγ, rod PDE6 and GRK1 to outer segments in rod photoreceptors and subsequent retinal degeneration." (PMID 33681987, 2021). "Thus, although ARL3 is not a common cause of retinal degeneration in humans, it is a strong prior candidate gene." (PMID 33748123, 2021). "Collectively, our findings suggest that RP2 and Arl3 regulate the trafficking of specific kinesins to cilia tips and provide additional evidence that TRIDs could be clinically beneficial for patients with this retinal degeneration." (PMID 28444310, 2017). "Therefore, for ARL3-G70E, in addition to deficient ciliary INPP5E, altered PDE6δ and UNC119 function caused by aberrant ARL3-GTP cycling within the cell could also contribute to retinal degeneration." (PMID 40037334, 2025).
retinitis pigmentosa (5 papers, 2016 to 2024). Retinitis pigmentosa (RP) is an inherited retinal dystrophy leading to progressive loss of the photoreceptors and retinal pigment epithelium and resulting in blindness usually after several decades. "previously reported the heterozygous missense variant c.269A>G (p.Tyr90Cys) in ARL3 in a European-descent pedigree with non-syndromic retinitis pigmentosa." (PMID 30269812, 2018). "Thus, although the connection between the de novo ARL3 variant and retinitis pigmentosa remains unexplained, it seems that bi-allelic ARL3 deleterious variants are sufficient to cause JBTS." (PMID 30269812, 2018). "Given its expression pattern, binding partners, and biochemical, ARL3 is a strong a priori candidate gene for retinitis pigmentosa in humans." (PMID 26964041, 2016). "By checking the background information, we found that ARL3 can directly bind to RP2, and RP2 can act as the GTP-enzyme activating protein of ARL3, thus affecting intracellular microtubule regulation and protein transport, which can cause diseases such as retinitis pigmentosa." (PMID 37602882, 2023).
glioma (4 papers, 2019 to 2023). A benign or malignant brain and spinal cord tumor that arises from glial cells (astrocytes, oligodendrocytes, ependymal cells). "In this study, we identified ARL3 as a prognostic marker for glioma, and constructed a nomogram and risk classification system." (PMID 31234870, 2019). "In conclusion, our study demonstrated that ARL3 expression was decreased in glioma samples and was associated with tumor grade." (PMID 31234870, 2019). "In the present study, we discovered that ARL3 expression was decreased in glioma samples and was associated with tumor grade." (PMID 31234870, 2019). "In view of the prognostic value of ARL3 in glioma, we constructed a nomogram and risk classification system for predicting 3- and 5-year survival." (PMID 31234870, 2019). "ARL3 expression was downregulated in glioma, and associated with poor prognosis in glioma patients." (PMID 31234870, 2019). "At the same time, another article have confirmed that ARL3 is a prognostic biomarker for glioma, and its low expression predicts poor prognosis." (PMID 37602882, 2023). "Considering the clinical factors of glioma, these parameters (ARL3 expression level, age, sex, WHO grade and IDH status) were included in the predictive model." (PMID 31234870, 2019). "Since it is well established that tumor-infiltrating immune cells play a key role in tumor development, the mechanism by which ARL3 influences infiltrating immune cells in the glioma microenvironment should be investigated in future studies." (PMID 31234870, 2019). "Data from The Cancer Genome Atlas (TCGA), Chinese Glioma Genome Atlas (CGGA) and Repository for Molecular Brain Neoplasia Data (REMBRANDT) databases were employed to investigate ARL3 expression and its roles in glioma prognosis." (PMID 31234870, 2019). "The results demonstrated that low ARL3 expression was negatively correlated with glioma patient outcome." (PMID 31234870, 2019). "In terms of chemotherapy, the survival time in the high ARL3 expression group was longer than that in the low ARL3 expression group among glioma patients as well as in primary GBM patients." (PMID 31234870, 2019). "The results in the CGGA revealed that the glioma patients receiving radiotherapy in the high ARL3 expression group had a better prognosis than patients in the low ARL3 expression group." (PMID 31234870, 2019). "RT-PCR and immunohistochemistry were performed to examine the expression level of ARL3 in glioma samples." (PMID 31234870, 2019). "Another novel finding of this study is that ARL3 is involved in the glioma immune microenvironment and angiogenesis." (PMID 31234870, 2019). "To explore the prognostic value of ARL3, we collected survival data from 46 patients with different grades of glioma and investigated the relationship between ARL3 expression level and prognosis." (PMID 31234870, 2019). "In this study, we investigated ARL3 expression and its roles in glioma prognosis using clinical samples and data from The Cancer Genome Atlas (TCGA), Chinese Glioma Genome Atlas (CGGA) and Repository for Molecular Brain Neoplasia Data (REMBRANDT) databases." (PMID 31234870, 2019). "To extend these observations, we examined ARL3 expression in different subtypes of glioma in the TCGA, CGGA and REMBRANDT datasets." (PMID 31234870, 2019). "The results demonstrated that elevated ARL3 expression was clinically correlated with favorable outcomes of glioma patients." (PMID 31234870, 2019). "Regarding biological function, we proved that ARL3 negatively regulates angiogenesis and influences immune cell infiltration into the glioma microenvironment." (PMID 31234870, 2019). "Taken together, these results suggest a potential role of ARL3 as a prognostic marker and therapeutic target for glioma." (PMID 31234870, 2019). "Taken together, these results suggest the potential value of ARL3 as a marker in the outcome prediction of glioma patients." (PMID 31234870, 2019).